ALK (ALK receptor tyrosine kinase)
Diseases named in the same sentence as ALK in open-access papers (continued):
Sharing a sentence is not in itself a finding about the gene and the disease.
lung cancer (continued). "In the present study, we recruited a total of 59 patients with lung cancer and analyzed the efficacy and safety of postoperative targeted therapy in ALK-positive lung cancer." (PMID 37221218, 2023). "In this study, we performed proteomic and GAG-omic analysis on 22 tissue regions from 7 ALK rearranged lung cancer patients, grouped according to different histopathological aspects (morphology, mucin and stroma content)." (PMID 37069213, 2023). "Lung cancer is characterised by genetic modifications such as mutations inthe epidermal growth factor receptor (EGFR), fusion or rearrangement of the anaplastic lymphoma kinase (ALK), and various other abnormalities." (PMID 37928493, 2023). "Patients with ALK-positive lung cancer tend to have a higher response rate and longer progression-free survival with ALK-targeted therapies." (PMID 38202898, 2023). "The 2016 Guideline for Treatment of Lung Cancer of The Japan Lung Cancer Society recommends testing patients with non-squamous NSCLC for multiple biomarkers, including EGFR gene mutation, ALK fusion, and programmed cell death 1 (PD-L1) expression." (PMID 37658334, 2023). "ALK-positive large-cell neuroendocrine carcinoma (LCNEC) is an exceptionally rare form of lung cancer." (PMID 37456922, 2023). "In this study, among the several mechanisms of adaptive resistance in ALK-rearranged lung cancer cells, we focused on EGFR signaling." (PMID 36702855, 2023). "Anaplastic lymphoma kinase (ALK) fusion gene-positive lung cancer often shows brain metastasis at initial diagnosis or during the course of treatment." (PMID 38158887, 2023). "Another driver oncogenic molecule, the anaplastic lymphoma kinase (ALK) gene, is more commonly implicated in pregnancy-associated lung cancers." (PMID 37916176, 2023). "These factors are more prevalent in ALK-negative lung cancer, as these patients are usually older than ALK-positive patients, possibly explaining why the multivariate analysis did not reveal an association between ALK rearrangement and ATE in our study." (PMID 37014824, 2023). "This study provides new insights regarding tumor evolution due to EGFR signaling after lorlatinib treatment and the development of combined therapeutic strategies for ALK-rearranged lung cancer." (PMID 36702855, 2023). "Epidermal growth factor receptor (EGFR), anaplastic lymphoma kinase (ALK) and v-Ki-ras2 Kirsten rat sarcoma viral oncogene (KRAS) are the most common mutated oncogenes associated with lung cancer BM." (PMID 37508989, 2023). "Given the dense scientific debate on the role of EGFR and ALK mutations in NSCLC, aimed studies on BMs derived from this specific family of lung cancer should be carried out to explore their impact on diagnosis and treatment prognosis." (PMID 37240478, 2023). "EGFR inhibition halted ALK-rearranged lung cancer cell proliferation by enhancing ALK inhibition-induced apoptosis via suppression of Bcl-xL." (PMID 36702855, 2023). "According to previous studies, ALK-rearranged lung cancer patients have similar or worse survival outcomes than EGFR-mutated patients." (PMID 37409244, 2023). "The safety and efficacy of this combination therapy will be validated in a future clinical setting for untreated ALK-rearranged lung cancer." (PMID 36702855, 2023). "Anaplastic lymphoma kinase (ALK) is a critical driver of lung cancer development and is currently the "gold standard" target for non-small cell lung cancer treatment." (PMID 37869075, 2023). "Inhibition of ALK is initially effective in patients with ALK-driven lung cancer but resistance often arises." (PMID 37147298, 2023). "Compared with chemotherapy, all ALK inhibitors can significantly improve the PFS of lung cancer patients in this group." (PMID 36874629, 2023). "Patients with ALK-positive lung cancer have been reported to have some clinical and radiological features, such as younger age, no or light smoking history, lower GGO proportion, lobulated margins, and lymph node involvement." (PMID 36823653, 2023).
lung cancer (continued). "We constructed a CCCN and CFN from measurements of phosphorylation, acetylation, and ubiquitination in 10 different lung cancer cell lines with driver mutations in EGFR, ALK, ERBB2/HER2, ROS1, and DDR2, treated with four different TKIs." (PMID 36996232, 2023). "In this study, we investigated the therapeutic effect and safety of crizotinib through comparing with postoperative adjuvant chemotherapy in ALK-positive lung cancer patients at stage II–IIIA and IB." (PMID 37221218, 2023). "In recent years, with the development, marketing and clinical application of ALK Tyrosine Kinase Inhibitors (TKIs), the ALK pathway has made a major breakthrough in the field of lung cancer treatment." (PMID 37658352, 2023). "As targeted agents continue to be developed, there is evidence that inhibitors of ALK, such as crizotinib and alectinib, can demonstrate efficacy in the treatment of nonsmall cell lung cancer and myofibroblastic tumors due to ALK rearrangements." (PMID 37367052, 2023). "Now, various drugs can be used for first-line treatment options in advanced lung cancer with ALK rearrangement, from the initial generation of crizotinib to the second generation of ceritinib, alectinib, and brigatinib, to the third generation of lorlatinib." (PMID 37409244, 2023). "Since the discovery of ALK-rearranged lung cancers in 2007, several ALK inhibitors have been developed and approved for clinical use, such as the first-generation ALK inhibitor Crizotinib (Xalkori), or the second-generation inhibitor Alectinib (Alecensa)." (PMID 37511126, 2023). "In lung cancer, the discovery of driver mutations in genes, such as the epidermal growth factor receptor (EGFR) and anaplastic lymphoma kinase (ALK), has been transformative." (PMID 37686423, 2023). "Given the metastatic survival data on lung cancer treated with ALK inhibitors, it is important to manage the toxicity associated with these treatments." (PMID 37894307, 2023). "Overall, our pilot study provides an excellent starting point for further studies investigating larger number of ALK rearranged lung cancer patients, as well as for proteomic and GAG-omic characterization of other gene rearrangements causing adenocarcinoma." (PMID 37069213, 2023). "In this study, we performed a retrospective study to investigate the therapeutic effect, safety and optimal treatment regimen of ALK inhibitor in ALK-positive lung cancer patients." (PMID 37221218, 2023). "Recombinant HB-EGF reduced the sensitivity of ALK-rearranged lung cancer cells to lorlatinib, whereas EGFR knockdown restored the sensitivity of A925L and H2228 cells to lorlatinib in the presence of HB-EGF." (PMID 36702855, 2023). "The International Association for the Study of Lung Cancer (IASLC) recommends to test EGFR mutations and ALK and ROS1 fusions." (PMID 36899890, 2023). "In each case of ALK fusion gene-positive lung cancer with brain metastases, brigatinib showed a high efficacy and was well-tolerated after previous ALK-TKI and for bulky lesions." (PMID 38158887, 2023). "Combined inhibition of both ALK and PI3Kβ therefore represents a promising approach to improve clinical responses in ALK‐rearranged lung cancers." (PMID 36423211, 2023). "Our study identified that crizotinib-based postoperative targeted therapy helps improve the prognosis of patients with ALK-positive lung cancer, confirming that postoperative targeted therapy can be considered an effective and feasible therapeutic alternative." (PMID 37221218, 2023). "ALK (anaplastic lymphoma kinase) is a receptor tyrosine kinase, which plays an important role in lung cancer." (PMID 37345194, 2023).
lung cancer (continued). "The combination of ezatiostat, a specific GSTP1 inhibitor, and crizotinib, an ALK inhibitor, can regulate the activity of lung cancer stem cells." (PMID 37941550, 2023). "For lung cancer, most notably EGFR, ALK and PD-L1 expression has had a significant impact on management, however, there is very limited data available of molecular profiles of lung cancer patients in SSA." (PMID 37368872, 2023). "We identified selective PI3Kβ inhibition as a promising novel target to potentiate ALK inhibition responses in ALK‐rearranged lung cancer." (PMID 36423211, 2023). "This study helps confirm the effective and feasible therapeutic approach of postoperative targeted therapy in ALK-positive lung cancer, which is beneficial to improve prognosis in patients with lung cancer." (PMID 37221218, 2023). "Alectinib is the first line of treatment for patients with ALK-positive lung cancer, but the survival rate beyond 2–3 years is low." (PMID 37339995, 2023). "The incidence of anaplastic lymphoma kinase (ALK)-rearranged mutations and epidermal growth factor receptor (EGFR)-rearranged mutations in lung cancer patients is around 5% and 15%, respectively." (PMID 37835467, 2023). "We are fortunate that there have been advances in ALK tyrosine kinase inhibitor (ALK-TKI) targeted therapies for ALK-positive lung cancer over the last decade." (PMID 37409244, 2023). "To date, no direct comparisons have compared the effectiveness of all ALK inhibitors (ALKis) against ALK‐positive non‐small cell lung cancer (NSCLC)." (PMID 37334877, 2023). "In lung cancer, we and other groups reported that activation of HGF/MET causes resistance to EGFR‐TKIs and ALK‐TKIs in EGFR‐mutated NSCLC and ALK‐rearranged NSCLC, respectively." (PMID 36416133, 2023). "In contrast, transcriptome analysis and siRNA library showed that diverse epigenetic mechanisms intricately affect the adaptive resistance in ALK-rearranged lung cancer, indicating that EGFR is involved in part of the adaptive response to lorlatinib." (PMID 36702855, 2023). "As expected, EGF treatment decreased the effect of ALKi on cell viability in all tested ALK‐rearranged lung cancer cell models." (PMID 36423211, 2023). "A surge of potential therapeutic targets of lung cancer such as ALK, EGFR, BRAF, c-Ros oncogene 1 (ROS1), MET, and RET came to light in the last decade." (PMID 37568796, 2023). "Anaplastic lymphoma kinase (ALK) has been shown to be a primary driver of disease progression in lung cancer, and ALK inhibitors are effective therapeutics in aberrant ALK-expressing tumors." (PMID 38144528, 2023). "We aimed to address these knowledge gaps and investigate the association between ALK-positive NSCLC and VTE/ATE in a large nationwide cohort of patients with advanced lung cancer treated in tertiary and community-based centers." (PMID 37014824, 2023). "In summary, the emerging evidence of LLPS in ALK fusions, particularly EML4-ALK variant 1, emphasizes the significance of this cellular process in the pathogenesis of lung cancer." (PMID 37705755, 2023). "In conclusion, by systematically analysing the DNA‐based NGS data of ALK rearrangements in lung cancer patients, we identified variable and uncommon genomic breakpoints of ALK and its 5′partner genes." (PMID 36423218, 2023). "ESMO and NCCN recommend alectinib, brigatinib, or lorlatinib as a first-line treatment for metastatic ALK-rearranged lung cancer." (PMID 37894307, 2023). "Diverse genomic breakpoints of ALK rearrangements were identified by DNA‐based next‐generation sequencing (NGS) in non‐small cell lung cancer." (PMID 36423218, 2023). "The observation aligns with the finding that RET fusion-positive lung carcinomas displayed a higher prevalence of poorly differentiated tumors in comparison to those with ALK or EGFR alterations." (PMID 38132167, 2023).
lung cancer (continued). "We utilized pentaplex panel testing for 23 lung carcinomas, 23 sarcomas, 4 thyroid carcinomas, 3 salivary gland tumors, and 3 pancreatic carcinomas with oncogenic gene translocations (ALK: 31; ROS1 10; RET: 9; NTRK1: 2; NTRK3: 4)." (PMID 37686416, 2023). "RET fusion-positive lung carcinomas exhibit poorer differentiated tumors compared to those with ALK or EGFR alterations." (PMID 38132167, 2023). "The growing efficacy and availability of new targeted systemic therapies have markedly improved the prognosis of metastatic lung cancer patients harboring ALK rearrangements." (PMID 35158987, 2022). "Among the tyrosine kinase inhibitors (TKIs), ALK inhibitors have achieved the longest survival times in patients undergoing systemic treatment for advanced lung cancer." (PMID 35806325, 2022). "BCL-XL knockdown using siRNA (siBCL-XL) significantly increased apoptosis induction and decreased viability of ALK-rearranged lung cancer cells, compared to those treated with alectinib alone." (PMID 35228642, 2022). "In another study, the antiproliferative effect of TAE684, a potent second generation ALK inhibitor that overcomes crizotinib resistance, was augmented by radiotherapy in EML4-ALK positive lung cancer cells." (PMID 35158987, 2022). "ALK-translocated advanced lung cancer is the most interesting model, having achieved the longest overall survival." (PMID 35806325, 2022). "In line with previous reports, our analysis recapitulated the key targetable oncogenic fusion events in lung cancers, with a 4.2% frequency of ALK fusions, 1.3% of RET fusions, and 1.2% of ROS1 fusions." (PMID 36369474, 2022). "Our findings provide new insights into combined therapeutic strategies aimed at tumor eradication in ALK-rearranged lung cancer." (PMID 35228642, 2022). "For lung cancer metastases, ALK-protein and EGF-receptor (EGFR) were analyzed most frequently, with 31 conclusive cases out of 32 analyzed (97%)." (PMID 36605448, 2022). "Many preclinical studies have found higher PD-L1 expression on tumor cells in patients with ALK rearranged NSCLC than on other types of lung cancer cells, but clinical trials of single agent immunotherapy have not yielded significant clinical benefit." (PMID 36591504, 2022). "Subsequently, we assessed the pharmacological effects of YHO-1701 in ALK-rearranged lung cancer cells via inhibition of STAT3 nuclear translocation." (PMID 35228642, 2022). "ALK mutations are mutually exclusive with EGFR and KRAS mutations in many patients, positioning ALK as the primary target for treatment in ALK-positive lung cancers." (PMID 36230484, 2022). "More than 60% of nonsmall cell lung cancer (NSCLC) patients show a positive response to the first ALK inhibitor, crizotinib, which has been used as the standard treatment for newly diagnosed patients with ALK rearrangement." (PMID 34845836, 2022). "In summary, the acquired mechanisms of resistance to lorlatinib with ALK-rearranged lung cancers can be diverse and complex." (PMID 35459209, 2022). "Anaplastic lymphoma kinase (ALK) gene fusion, an important driver gene alteration leading to the development of lung cancer, occurs in 5% of nonsmall cell lung cancer (NSCLC) cases in China." (PMID 36042596, 2022). "The increased proclivity of ALK altered nonsmallcell lung cancer to particularly metastasis to the brain is another example of molecular subtype affecting metastatic patterns." (PMID 35019232, 2022). "Taking into account potential cancer type differences, we found that ROS1 (63% vs. 44%; Fisher’s exact test P < 0.0001) and ALK fusions (50% vs. 44%, Fisher’s exact test P = 0.006) remain more prevalent in female lung cancer patients." (PMID 36369474, 2022). "Anaplastic lymphoma kinase (ALK) fusion is a prognostic indicator for patients with non‐small cell lung cancer (NSCLC) receiving tyrosine kinase inhibitors (TKIs)." (PMID 35616090, 2022).
lung cancer (continued). "In summary, the mechanisms underlying treatment-induced adaptive cancer cell survival in residual tumors of ALK-rearranged lung cancer are predominantly dependent on STAT3 activity and subsequent transcriptional regulation of apoptosis." (PMID 35228642, 2022). "Over the last 14 years, we have seen the treatment and survival of ALK-positive lung cancers revolutionized by the differential treatment of this important sub-population with high-impact targeted ALKi therapies." (PMID 36003760, 2022). "This study shows clinical efficacy of the combination of alectinib and bevacizumab with acceptable toxicity in patients with ALK-positive lung cancer after ALK-TKI failure." (PMID 36612200, 2022). "In contrast to the potent efficacy of ALK-TKIs, there are few reports on the effectiveness of ICIs for ALK-rearranged lung cancer." (PMID 35407463, 2022). "Patients with ALK‐rearranged non‐small cell lung cancer (ALK+ NSCLC) inevitably acquire resistance to ALK inhibitors." (PMID 35437925, 2022). "We have done research on PubMed and also looked up on the internet using lung cancer, ALK, and salvage surgery as key words." (PMID 35366157, 2022). "We investigated the functional roles of STAT3 in the adaptive survival of ALK-rearranged lung cancer cells by evaluating apoptosis induction with STAT3 knockdown." (PMID 35228642, 2022). "Patients with Anaplastic lymphoma kinase (ALK)-positive lung cancer after progression of ALK-tyrosine kinase inhibitor have limited treatment options." (PMID 36612200, 2022). "Ablative and hypofractionated radiotherapy is one strategy for ALK+ lung cancer, since many ALK+ NSCLC patients treated with ALK TKIs experienced local disease progression." (PMID 35463328, 2022). "It has been reported that combining crizotinib with everolimus synergistically inhibits the proliferation of ALK-positive anaplastic large cell lymphoma and lung cancer cells." (PMID 36167821, 2022). "EGFR and ALK inhibitors have become the mainstays of treatment in lung cancer therapy, while in recent years a new class of drugs has been able to target the once “un-druggable” KRAS mutation." (PMID 36230484, 2022). "Collectively, these results indicate that YHO-1701 effectively suppresses cell adaptation to ALK-TKIs driven by STAT3 re-activation and induces apoptosis in residual ALK-rearranged lung cancer cells." (PMID 35228642, 2022). "Many therapeutically actionable mutational drivers have been identified in this class of lung cancer, such as EGFR and ALK mutations, that allow for targeted therapies for these subsets of lung cancer patients." (PMID 35804837, 2022). "Anaplastic lymphoma kinase-tyrosine kinase inhibitors (ALK-TKIs) have shown dramatic efficacy in patients with ALK-rearranged lung cancer; however, complete response in these patients is rare." (PMID 35042943, 2022). "In particular, the rearrangement or fusion of the anaplastic lymphoma receptor tyrosine kinase (ALK) gene was first identified in 2007 as a driver of lung cancer." (PMID 35626451, 2022). "Ceritinib is an ALK inhibitor approved by the FDA for the treatment of ALK+ metastatic non–small-cell lung cancer (NSCLC) in 2014." (PMID 35768871, 2022). "Interactions with the immune system also appears critical in mediating the response to tyrosine kinase inhibitors in ALK positive lung cancer." (PMID 36686777, 2022). "The remainder of lung cancers, the non-small cell lung cancers (NSCLC), express amplifying EGFR (epidermal growth factor receptor) mutations in some 10% and amplifying ALK rearrangements in 4–7%." (PMID 35902427, 2022). "Similar findings have also been reported in other ROS1 and ALK lung cancer cohorts, further supporting the notion that ROS1‐rearranged and ALK‐rearranged NSCLCs are specifically associated with an elevated risk of thromboembolic events." (PMID 35510711, 2022). "ALK gene rearrangements were more common in lung cancer at advanced stages, in accordance with a prior study." (PMID 36338735, 2022).